WFDC21P (WAP four-disulfide core domain 21, pseudogene)
Synonyms: LOC645638; lnc-DC; LNCDC
Gene: Transcribed unitary pseudogene on chromosome 17 (60,085,109 to 60,088,286, reverse strand). Ensembl gene ENSG00000261040.
Diseases named in the same sentence as WFDC21P in open-access papers:
WFDC21P is named in the same sentence as 11 diseases in open-access papers, as found by Europe PMC text mining. Sharing a sentence is not in itself a finding about the gene and the disease. The quoted sentences say what the papers report.
gastric cancer (3 papers, 2022 to 2024). A primary or metastatic malignant neoplasm involving the stomach. "Accordingly, we supposed that WFDC21P may also bind to proteins to regulate gastric cancer malignant behaviors." (PMID 38528582, 2024). "Right after, GEPIA database was used to verify the expression of WFDC21P in gastric cancer." (PMID 38528582, 2024).
lung carcinoma (2 papers, 2021 to 2022). "In this study, we found that miR-4293 downregulates the degradation of WFDC21P by directly mediating DCP2, which plays important role in the tumorigenesis of lung carcinoma." (PMID 34301920, 2021). "Therefore, we assumed that WFDC21P may be regulated by DCP2, and is involved in the pathogenesis of lung cancer." (PMID 34301920, 2021).
tumor (3 papers, 2020 to 2025). "Other research shows that miR-4293 regulating WFDC21P through downregulate DCP-2 while miR-4293 promotes tumor cell proliferation and metastasis but suppresses apoptosis." (PMID 40895564, 2025). "We further investigated whether WFDC21P regulates HCC tumorigenesis by targeting PFKP in xenograft tumor models." (PMID 31959898, 2020). "In conclusion, we identified a new candidate oncogenic lncRNA WFDC21P that promotes tumor progression through WFDC21P/Ran/Akt/GSK3β/β-catenin axis and that is positively regulated by transcription factor FOXP3 in GC, which may provide a novel biomarker and therapeutic target for GC." (PMID 34601496, 2021).
cancer (2 papers, 2021 to 2025). A tumor composed of atypical neoplastic, often pleomorphic cells that invade other tissues. "Accordingly, we observed that DCP2 can bind to WFDC21P, a long non-coding RNA, to participate in cancer pathogenesis." (PMID 34301920, 2021). "As a member of the WFDC family, known for roles in immune modulation and cancer, WFDC21P may function as a noncoding regulator, such as a miRNA sponge or scaffold for RNA-protein complexes." (PMID 41424764, 2025). "Additionally, we also found that the expression of WFDC21P in cancer cell lines (A549, H1299, and H1975) was markedly elevated compared with human bronchial epithelial cells (HBE)." (PMID 34301920, 2021).
WFDC21P also shares sentences with these, for which no sentence is quoted: bladder cancer (1 paper); breast carcinoma (1); colon cancer (1); esophageal cancer (1); multiple sclerosis (1); pancreatic cancer (1); rheumatoid arthritis (1).